VCP (valosin containing protein)
Diseases named in the same sentence as VCP in open-access papers (continued):
Sharing a sentence is not in itself a finding about the gene and the disease.
cancer (continued). "Similarly, the Smy2 homologs GIGYF1 and -2 affect the transcription stress response in human cells and regulate the function of the Cdc48 homolog VCP/p97, presently being explored as a target for cancer therapy." (PMID 36288698, 2022). "For example, ASCC3, ABCE1, ANKZF1, VCP have been shown to be overexpressed in cancer cells." (PMID 36187485, 2022). "The inhibition of VCP has been suggested as a treatment of metastasis in certain cancers." (PMID 35841038, 2022). "However, VCP/p97 interacts with many cofactors to participate in different cellular processes that are critical for cancer cell survival and aggressiveness." (PMID 34576340, 2021). "Previous reports showed that VCP contributes to cancer progression by regulating NF-κB signaling." (PMID 34560900, 2021). "Moreover, up-regulation of VCP in cancer tissues was detected in 64.3% (56/87) cases, as compared with adjacent normal tissues." (PMID 34560900, 2021). "The identified proteins are involved in cell migration (Collagen alpha-2(I) chain), effected cancer cell motility (Actin), promotion of metastasis (Valosin-containing protein), cancer cell viability, angiogenesis (Collagen alpha-3(VI) chain) and tumor progression (Collagen alpha-2(I) chain)." (PMID 34681132, 2021). "However, with VCP inhibitors already in phase I clinical trials for cancer treatment, it is important to recognize the therapeutic potential for these devastating and hitherto incurable diseases." (PMID 34396115, 2021). "Indeed, VCP/p97 is reported to be overexpressed in many cancer types and is considered a potential cancer biomarker and therapeutic target." (PMID 34576340, 2021). "Given that new generation VCP-targeting drugs are currently evaluated in clinical trials for cancer treatment, VCP may constitute an attractive broad-spectrum antiviral target in drug repurposing approaches." (PMID 34696522, 2021). "Interestingly, although the aberrant expression of VCP has been shown to contribute to cancer progression at different stages, the role of VCP in the pathogenesis of cancers appears controversial." (PMID 32481679, 2020). "High level of the multifunctional AAA-ATPase p97/VCP is often correlated to the development of cancer; however, the underlying mechanism is not understood completely." (PMID 32002125, 2020). "Based on these results, VCP is now considering as an important target for cancer treatment." (PMID 32481679, 2020). "In recent reports, altered p97/VCP expression was reportedly observed in specific cancer cells." (PMID 32002125, 2020). "Inhibition of VCP induces cancer cell growth arrest and apoptosis." (PMID 31456945, 2019). "Although clinical trials of CB-5083 for solid tumors and hematological malignancies were recently prematurely terminated due to the off-target effect on PDE6 resulting in ocular dysfunction, additional VCP inhibitors are being explored as clinical leads for cancer treatment." (PMID 31358864, 2019). "We have not detected these proteins in our exosomes, since their distribution could be tissue-specific, but the targeting of VCP could decrease exosome generation in several tumor models, offering an interesting new avenue for cancer treatment." (PMID 27086912, 2016). "These factors pose significant challenge in using VCP as a target for anti-cancer therapeutics." (PMID 27434122, 2016). "Thus, depletion of VCP triggers cancer cell death in part through inadequate control of protein synthesis and amino acid metabolism, and allows it to have implications for the development of anti-cancer therapies." (PMID 27072583, 2016). "There are several issues that come with inhibiting VCP in normal non-cancer cells." (PMID 27434122, 2016). "Hence, in this study we synthesized a dendrimer-based nano-drug formulation to increase specificity and provide sustained targeted-delivery of potent VCP inhibitor to the cancer cells." (PMID 27434122, 2016).
cancer (continued). "It has been shown recently that VCP inhibition by the specific inhibitor DBeQ or also by sorafenib could have therapeutic interest in cancer treatment." (PMID 27086912, 2016). "Thus, an ATP-competitive and an allosteric VCP inhibitor effectively kill cancer cell lines of different tissue origins, including bortezomib-adapted and clinically bortezomib-resistant cells." (PMID 26720340, 2015). "However, the mechanisms by which pharmacological VCP depletion induces cancer cell death, and how they differ from those mediated by proteasome inhibition, remain incompletely understood." (PMID 26720340, 2015). "Thus, depletion of VCP enzymatic activity triggers cancer cell death in part through inadequate regulation of protein synthesis and amino acid metabolism." (PMID 26720340, 2015). "Given the nature of its biological functions, several authors have proposed that VCP could represent a pharmacological target for the treatment of cancer." (PMID 26104798, 2015). "Valosin containing protein (VCP) is a critical mediator of protein homeostasis and may represent a valuable therapeutic target for several forms of cancer." (PMID 26104798, 2015). "The data provide novel insights into the maintenance of intracellular proteostasis by VCP and may have implications for the development of anti-cancer therapies." (PMID 26720340, 2015). "This correlation suggests that the level of VCP expression could be used as potential marker for the progression of these cancers." (PMID 23383273, 2013). "The aggresome pathway and VCP inhibitors are emerging fields in cancer therapy." (PMID 23383273, 2013). "Nevertheless, overexpression of VCP has recently been evidenced in situ in a wide array of human cancer types, and analyses of large patient cohorts demonstrated significantly increased expression levels of VCP by tumor cells often correlate with disease progression." (PMID 22870330, 2012). "In addition to essential functions in homeostasis, VCP was shown to regulate the half-life and levels of several proteins with cancer-modulating functions." (PMID 22870330, 2012). "VCP is important player in cancer cell survival and can be used as a target for cancer therapy." (PMID 23233838, 2012). "Mutations and/or misregulation of VCP functions in cancer cells are still not well characterized, as are their possible causative effects in tumorigenesis." (PMID 22870330, 2012). "We report that VCP is overexpressed in the serum of cancer patients, and that it may represent a new clinically useful marker for cancer detection." (PMID 22870330, 2012). "The upregulation of KDR is consistent with the previously discussed role of VCP in regulating angiogenesis and vascular permeability and highlights its involvement in pathological conditions characterized by aberrant angiogenesis, such as in cancer and vascular diseases." (PMID 39802400, 2025). "In addition, knockout of the gene encoding VCP slows the growth of multiple cancer cell lines, including RMS cell lines, as represented in the Dependency Map project, a comprehensive CRISPR/Cas9-based analysis of pan-cancer genetic dependencies." (PMID 40879698, 2025). "Thus, VCP provides an attractive broad-spectrum antiviral target in drug repurposing approaches given that new VCP-targeting drugs are currently in clinical trials for cancer treatment." (PMID 40295816, 2024). "The VCP/USP2/FASN axis could emerge as a compelling therapeutic target in cancer treatment." (PMID 39489738, 2024). "However, research on VCP's ubiquitination in the context of cancer remains limited." (PMID 38495507, 2024). "Thus, VCP has been identified as a potential therapeutic target for many cancer types." (PMID 36923647, 2023). "Since VCP is a direct target of miR-198, we examined whether exogenous administration of miR-198 could alter autophagy through VCP targeting and sensitize cancer cells to gemcitabine." (PMID 37631252, 2023).
cancer (continued). "Hence, targeting VCP activity has emerged as a promising therapeutic option in cancer." (PMID 36196920, 2022). "Thus, as a major regulator of mitochondria, VCP could also play critical roles in the pathogenesis of cancers." (PMID 32481679, 2020). "In addition to the imbalances in the proteasomal pathway, p97/VCP may trigger aberrant migration of cancer cells by altering actin-related cell migratory characteristics." (PMID 32002125, 2020). "In addition, the VCP expression level was also shown to be upregulated in some cancers, mainly in response to the increased burden of protein degradation, indicating that VCP inhibition could be a promising therapeutic approach to cancer management." (PMID 32481679, 2020). "This could be explained by the fact that VCP is up-regulated by damage-induced protein stress signals that are elevated in cancer cells and that it helps in the clearance of abundant, misfolded/aggregate-prone, and potentially toxic proteins from malignant cells and facilitates their survival." (PMID 26934314, 2016). "This broad involvement of VCP in intracellular protein turnover, combined with observations of aberrant VCP expression in different cancers, suggests that VCP inhibitors may overcome some limitations of proteasome inhibitors by affecting multiple proteostatic mechanisms simultaneously." (PMID 26720340, 2015). "Furthermore they analyzed the intensity of immunochemistry staining of the specimens by comparison to non-carcinoma endothelial cells and categorized as follows: weaker (VCP-expression level 1) or equal to or stronger (level 2) than expression in non-carcinoma endothelial cells." (PMID 25463965, 2014). "Additionally, VCP could be used for diagnosis in conjunction with more cancer type-specific markers to increase the overall sensitivity of the assay." (PMID 22870330, 2012). "Moreover, VCP overexpression is also related to cancer, inflammation and NFκB activation." (PMID 21085581, 2010). "Interestingly, RQC factors can display opposing functions in cancer development and suppression depending on specific circumstances, with some factors like ABCE1, ASCC3, and VCP suppressing cancer cell growth upon downregulation, while others like NEMF/Clbn and ZNF598 may promote it upon inhibition." (PMID 38798583, 2026). "As MSP1 (also called IBMPFD) caused by the mutations in VCP is a multisystem disease also affecting non-neuronal tissues, it raises the possibility that defects in the VCP nuclear functions may play a role in other major diseases, such as cancer." (PMID 38701207, 2024). "We demonstrate that VCP is a likely obligate co-factor of ASPSCR1::TFE3, one of the only such fusion oncoprotein co-factors identified in cancer biology." (PMID 38326311, 2024). "The development and use of pharmacological activators and inhibitors of IRE1α as well as VCP will allow for the careful titration of proteostasis and thus the optimization of the adaptive UPR or maximization of the terminal UPR for cancer therapy." (PMID 38727283, 2024). "NMS-873 targeting a region in VCP spans D1 and D2 domains of adjacent polymers to activate the unfolded protein response (UPR), interferes with autophagy and induces cancer cell death." (PMID 37606987, 2023). "When these VCP inhibitors are combined with Salubrinal treatment, ATF4 expression is enhanced leading to a greater increase in cancer apoptosis than with VCP inhibition alone." (PMID 37601686, 2023). "Recently, valosin-containing protein (VCP), also known at p97 AAA-ATPase, has emerged as a druggable target in cancer cells to affect their dependency on protein quality control." (PMID 35740614, 2022). "One potent and specific VCP inhibitor called NMS-873 was able to activate the unfolded protein response and thus interfered with autophagy, resulting in cancer cell death." (PMID 35841038, 2022).
cancer (continued). "Recent attempts to develop inhibitors for VCP/p97 (a distinct member of the type II AAA+ ATPase family, overexpressed in many cancers) identified two compounds that inhibit yeast VPS4 and human VPS4B." (PMID 31930723, 2020). "Accumulating evidence from clinical studies has revealed the prognostic value of VCP in a wide range of cancers, and demonstrated an enhanced ERAD and upregulated VCP expression in cancer cells." (PMID 32481679, 2020). "Together, our data point to an interconnected role of VCP/p97 and GCN2 in maintaining cancer cell metabolic and protein homoeostasis." (PMID 30626938, 2019). "Together, our data point to a pivotal and interconnected role of VCP/p97 and GCN2 in maintaining cancer cell metabolic and protein homoeostasis." (PMID 30626938, 2019). "NMS-873 is a very potent and specific inhibitor of VCP that has been shown to activate the unfolded protein response (UPR), interfere with autophagy and induce cancer cell death." (PMID 27434122, 2016). "In this study, we first aimed to compare two potent VCP inhibitors, NMS-873 and DBeQ, to determine which of these drugs provide better anti-cancer efficacy, once encapsulated in the dendrimer." (PMID 27434122, 2016). "This approach led to the identification of vasolin containing protein (VCP) as a potentially clinically relevant serum marker for human GCT, as well as for other forms of cancer." (PMID 22870330, 2012). "Additionally, although VCP suppression resulted in UPR activation in both RMS and other cancer contexts, inhibition with CB-5083 resulted in preferential UPR activation in tumor xenografts, rather than in the kidney." (PMID 40879698, 2025). "Initial omics‐based analyses have shown dysregulation in the expression of several RQC genes, such as ASCC3, ABCE1, ANKZF1, and VCP, in cancer cells; however, there is a lack of direct mechanistic studies." (PMID 40785597, 2025). "Furthermore, the dysregulation of RQC factor expression in cancer cells, including that of ASCC3, ANKZF1, ABCE1, and VCP, highlights the intricate nature of their roles in cancer." (PMID 39315278, 2024). "Our investigation into the differential vulnerability of cancer and non-transformed cells to VCP inhibition revealed distinct responses in the ISR between the two cell types." (PMID 38218922, 2024). "VCP regulates actin and cell motility via the Rho-ROCK dependent pathway in cancer development." (PMID 37606987, 2023). "Research on repurposing the old alcohol-aversion drug disulfiram (DSF) for cancer treatment has identified inhibition of NPL4, an adaptor of the p97/VCP segregase essential for turnover of proteins involved in multiple pathways, as an unsuspected cancer cell vulnerability." (PMID 32085572, 2020). "We verified elevated VCP protein expression not only in human adeno(AD)- and squamous(SQ)-NSCLC tissues but also in the NSCLC cell lines A549, H1229 and H1944 as compared to non-cancer, HBE (>5-fold) or Beas2b (≥2-fold) cell lines." (PMID 22216170, 2011). "In order to determine the molecular mechanism by which elevated VCP expression promotes these various cellular processes involved in NSCLC pathogenesis and progression, we examined the expression the levels of several cancer-related proteins." (PMID 22216170, 2011). "However, the precise mechanisms by which VCP inhibition selectively eradicates cancer cells while sparing non-cancerous cells have remained elusive." (PMID 38218922, 2024). "It has been reported that, in BC, PCa, and CC cells, PBX1 enhanced VCP transcription via binding its 5'‐flanking region, indicating that PBX1 might be involved in the regulation of cellular invasion and metastasis through VCP in these cancer types." (PMID 35068042, 2022). "However, only two studies reported VCP/p97 involvement in breast cancer, evidencing its elevated expression in cancer tissues without focusing on a specific breast cancer subtype." (PMID 35158912, 2022).
cancer (continued). "Overall expression of VCP was significantly increased in cancer cells compared to normal tissues." (PMID 26934314, 2016). "Thus, VCP serum levels were significantly increased in the majority of the tested cancer patients, including in some otherwise negative for established serum tumor markers." (PMID 22870330, 2012). "The findings show that targeting VCP could represent a new therapeutic avenue for HCC by addressing both tumor metabolism and immune dysfunction, offering a synergistic strategy that could improve the efficacy of existing immunotherapies and provide broader applications in cancer treatment." (PMID 39848960, 2025). "Therefore, they suggested that BPA might induce cancer progression rather than initiation and that VCP-mediated inflammatory pathways might disrupt thyroid function." (PMID 34576340, 2021).